KTI12 (KTI12 chromatin associated homolog)
Synonyms: SBBI81; TOT4; MGC20419
Tractability: PROTAC: ubiquitination databases record sites on it; its protein half-life has been measured.
Gene: Protein-coding gene on chromosome 1 (52,032,103 to 52,033,810, reverse strand). Ensembl gene ENSG00000198841.
Subcellular location (Human Protein Atlas): Cytoplasmic bodies; Nuclear speckles
Gene Ontology:
Molecular function: protein binding
Genetic constraint (gnomAD): Loss-of-function variants: 9 observed, 10.5 expected, observed/expected ratio (o/e) 0.86, 90% interval 0.51 to 1.49. The upper end of that interval is the gene's LOEUF score, 1.49, which puts it in group 6 of 6, group 1 being the genes least tolerant of losing a copy. Missense variants: 490 observed, 520.73 expected, observed/expected ratio (o/e) 0.94, 90% interval 0.87 to 1.01. Synonymous variants: 216 observed, 236.71 expected, observed/expected ratio (o/e) 0.91, 90% interval 0.82 to 1.02.
Homologues: Orthologues: macaque TXNDC12 (95% identical), pig KTI12 (85% identical), mouse Kti12 (76% identical), rat Kti12 (76% identical), zebrafish kti12 (44% identical), tropical clawed frog kti12 (42% identical), Caenorhabditis elegans Y57G11C.43 (27% identical), Drosophila melanogaster CG3587 (27% identical).
Diseases named in the same sentence as KTI12 in open-access papers:
KTI12 is named in the same sentence as 2 diseases in open-access papers, as found by Europe PMC text mining. Sharing a sentence is not in itself a finding about the gene and the disease. The quoted sentences say what the papers report.
colon cancer (1 paper, 2023). "The rest three genes KTI12, MAPKAPK3, and RPUSD2 haven’t been well-studied in colon cancer." (PMID 37701039, 2023).
KTI12 also shares sentences with these, for which no sentence is quoted: influenza (1 paper).